SHH (sonic hedgehog signaling molecule)
Diseases named in the same sentence as SHH in open-access papers (continued):
Sharing a sentence is not in itself a finding about the gene and the disease.
chordoma (4 papers, 2014 to 2024). Chordomas are rare malignant tumors arising from embryonic remnants of the notochord in axial skeleton. "Research has utilised immunohistochemistry (IHC), genetic analysis, and in situ hybridization to detect SHH pathway components in cranial and spinal chordoma samples." (PMID 39568072, 2024). "RNA-Seq and NanoString analyses confirmed the upregulation of PTCH1 and GLI1, further indicating SHH pathway activation in chordomas." (PMID 39568072, 2024). "These methods demonstrated overexpression of SHH and its downstream effectors, particularly GLI1, indicating active SHH signalling in chordomas." (PMID 39568072, 2024). "Limited studies have focused on the SHH pathway's role in chordoma formation and progression." (PMID 39568072, 2024). "In the current study, we investigated whether SHH signal cascade play a role in the formation of chordomas and their recurrences." (PMID 30769952, 2019). "Since it has been suggested that sonic hedgehog (SHH) may be involved in chordomagenesis, we screened 4 sacral chordomas and 3 chondrosarcomas for differentially expressed genes using a medium-dense cDNA microarray, which comprises genes associated with hedgehog signaling and cancer." (PMID 24452533, 2014). "Due to the high levels of SHH and GLI-1 expression in all investigated chordoma samples, the study suggests a possible autocrine ligand-dependent activation of the canonical HH signaling cascade." (PMID 30769952, 2019). "Our results suggest that Hedgehog-inhibitors, like SHH-, GLI- and SMO- inhibitors, might serve as a potential and effective target for the treatment of chordomas." (PMID 30769952, 2019). "None of the genes involved in the SHH pathway was transcriptionally activated in chordoma or chondrosarcoma." (PMID 24452533, 2014). "Furthermore, we could not demonstrate that our former candidate genes, HLXB9 and SHH, are overexpressed in chordoma." (PMID 24452533, 2014).
chronic myelogeneous leukemia (4 papers, 2012 to 2016). "HhP genes SHH, SMO, and GLI-1 are upregulated in chronic myeloid leukemia (CML) patients and are further elevated in blast crisis as compared to chronic-phase CML." (PMID 26483188, 2015).
cleft lip (4 papers, 2019 to 2023). Congenital defect in the upper lip where the maxillary prominence fails to merge with the merged medial nasal prominences. "SHH pathway disruption has been associated with the formation of multiple craniofacial abnormalities, including cleft lip." (PMID 33917041, 2021). "As it is depicted in literature, enhanced SHH signaling activity within cranial neural crest cells of the developing facial region has been associated with improper lip fusion and the formation of cleft lip." (PMID 33917041, 2021). "The statistically significant decrease of SHH in bilateral cleft lip connective tissue and cleft palate tissue could imply that SHH dysfunction might be more associated with the morphogenesis and tissue growth of these specific types of clefts postnatally and less with unilateral cleft lip." (PMID 37366674, 2023). "SHH signaling promotes cranial neural crest cell proliferation during the formation of the upper lip and disruption in this pathway can lead to cleft lip development." (PMID 33917041, 2021). "In previous studies, SHH signaling disturbances and loss of SHH function in the developing and growing lip epithelium have been associated with both UCL and BCL, while WNT9B functional disturbances have been associated with cleft lip and palate in mice." (PMID 37366674, 2023). "In this model of cleft lip, transcriptional profiling indicated that SHH pathway activity and Foxf2 expression corresponded with reduced mesenchymal cell proliferation in the medial nasal processes with Foxf2 being demonstrated to be a direct target of Shh signalling." (PMID 35226783, 2022). "Increase of SHH positive structures in the unilateral cleft lip affected connective tissue could indicate a disruption of correct tissue formation in cleft-affected tissue, which could have affected proper lip fusion and the development of cleft lip." (PMID 33917041, 2021). "After evaluation of cleft affected tissues, a statistically significant increase in the number of SHH positive structures was observed in patient connective tissue compared to the control group, which may indicate the possible role of SHH in formation of cleft lip." (PMID 33917041, 2021). "The aim of this study was to detect and compare the immunohistochemical expression of cleft candidate gene coded proteins (DLX4, MSX2, HOXB3, SHH, PAX7, SOX3, WNT3A, and FOXE1) in the non-syndromic unilateral cleft lip patient tissue and control group tissue." (PMID 33917041, 2021).
diabetes (4 papers, 2013 to 2025). "We propose that decreased SHH protein is an underlying cause of adverse penile remodeling and resultant ED, in patients with diabetes or following prostatectomy." (PMID 23967143, 2013). "While our study has established that the PPARs/SHH signaling axis plays a role in regulating wound healing in diabetes, certain limitations remain." (PMID 41216186, 2025). "In this study, we confirmed that impairment of primary cilia induced by diabetes directly led to inhibition of Hedgehog signaling, characterized by reduced SHH/Gli2 expression and increased Ptch1/Sufu expression." (PMID 36552853, 2022). "To test this hypothesis we examined corpora cavernosal tissue and quantified changes in SHH signaling and morphology from patient’s with Peyronie’s (control), diabetics and following prostatectomy." (PMID 23967143, 2013). "Additional insights indicated that KIAA0753 effectively restored osteoblast differentiation by directly interacting with SHH, OCN and Gli2, thereby activating the Hedgehog signalling pathway and mitigating the ubiquitination of Gli2 in diabetes." (PMID 39245790, 2024).
injury (4 papers, 2015 to 2022). Damage inflicted on the body as the direct or indirect result of an external force, with or without disruption of structural continuity. "Blocking of SHH signaling inhibits portal tract expansion, accumulation of liver progenitors, and liver cell proliferation.Its activation has also been found in hyperoxia and bleomycin induced lung injury although the mechanism is not clear yet." (PMID 26545089, 2015).
ischemia (4 papers, 2017 to 2024). A hypoperfusion of the BLOOD through an organ or tissue caused by a PATHOLOGIC CONSTRICTION or obstruction of its BLOOD VESSELS, or an absence of BLOOD CIRCULATION. "The beneficial effects of the activation of the SHH pathway in a porcine model of ischemia reperfusion opens a potentially interesting therapeutic prospective for patients suffering from a myocardial infarction to prevent the occurrence of reperfusion arrhythmias and reduce the infarct size." (PMID 32226535, 2020). "Treatment with SHH+ EPCs enhanced the incorporation of EPCs into the host blood vessels, suggesting a promising role of SHH in increasing the migration of transplanted EPCs into the site of ischemia to enhance angiogenesis and vasculogenesis." (PMID 30301174, 2018). "Therefore, the regulation of PRMT5 on SHH signaling may be one of the important mechanisms of its ischemia protection." (PMID 38372724, 2024).
Joubert syndrome (4 papers, 2013 to 2021). Joubert syndrome (JS) is characterized by congenital malformation of the brainstem and agenesis or hypoplasia of the cerebellar vermis leading to an abnormal respiratory pattern, nystagmus, hypotonia, ataxia, and delay in achieving motor milestones. "This defective processing of Gli3 with aberrant SHh signaling is similar to that seen in the brains of individuals with Joubert syndrome/Meckel syndrome." (PMID 33960602, 2021). "SHH signaling is dysregulated in cells from Joubert syndrome and Meckel syndrome patients." (PMID 29615573, 2017). "In addition to the well-known WNT and SHH pathways, the non-canonical WNT-planar cell polarity (PCP) pathway has also been implicated in the pathogenesis of Joubert syndrome." (PMID 24027500, 2013).
kidney cancer (4 papers, 2013 to 2020). Primary or metastatic malignant neoplasm involving the kidney. "In addition, it has been reported that SHH pathway closely correlates with kidney cancer." (PMID 29540668, 2018). "Both SHH and GLI1 have been reported to be overexpressed in gastric, bile duct, lung, and kidney cancers, among others." (PMID 33291316, 2020). "Finally, higher levels of renal CSCs markers and SHH pathway-related proteins were observed in kidney cancer tissues from smokers than non-smoking cancer tissues." (PMID 29540668, 2018).
lymph node metastasis (4 papers, 2015 to 2022). "Interestingly, low expression of SHH was significantly associated with advanced tumor invasion (pT staging, 85.5 % vs 62.5 %, P = 0.004), increased lymph node metastasis (pN staging, 89.9 % vs 72.9 %, P = 0.017)." (PMID 27039174, 2016). "In our study, we showed that positive staining for SHH and GLI1 was associated with advanced stage, lymph node metastasis and poor differentiation in NB specimens via IHC analysis." (PMID 25811359, 2015). "GLI3 encodes a zinc-finger transcription factor that modulates the sonic hedgehog (SHH) pathway, and one recent study on NSCLC demonstrated that overexpression of truncated GLI3 was significantly associated with lymph node metastasis and poor survival." (PMID 26647728, 2015). "They appear to pursue a benign clinical course in young adults, although in sporadic cases lymph node metastasis were described.The categorization of this new type of tumor may also lead to new therapeutic strategies, because they might be sensitive to SHH pathway inhibitors." (PMID 35387638, 2022). "Tumors with lymph node metastasis showed higher frequency of SHH and GLI1 positivity (SHH: 79% vs. 51%, P = 0.013; GLI1: 68% vs. 43%, P = 0.039)." (PMID 25811359, 2015).
Meckel syndrome (4 papers, 2017 to 2023). "In humans, impaired SHH signaling has been implicated in the cerebellar anomalies seen in both Joubert and Meckel Syndrome." (PMID 29615573, 2017).
metastatic disease (4 papers, 2011 to 2025). "It has recently been suggested that SHH signaling progresses during colon carcinogenesis and in metastatic disease whereas in normal colonic tissue, SHH signaling is involved in differentiation." (PMID 22087285, 2011).
odontogenic tumors (4 papers, 2013 to 2020). "Among them, fibroblast growth factor (FGF) and sonic hedgehog (SHH) are the most frequently altered genes in odontogenic neoplasms." (PMID 24716509, 2014). "Immunoreactivity for SHH, PTC, SMO, and GLI-1 was detected in both epithelial-derived odontogenic tumors and epithelial-mesenchymal-derived odontogenic tumors with or without dental hard tissue formation." (PMID 33374329, 2020).
rhabdoid tumor (4 papers, 2021 to 2025). An aggressive malignant embryonal neoplasm usually occurring during childhood. "The LM F2T2↑ rhabdoid tumor showed a massive upregulation of a unique growth factor program with selectively activated Wnt and SHH/ciliogenesis pathways, and an intermediate filament expression switch, with GFAP loss, and peripherin and vimentin massive overexpression." (PMID 33853673, 2021). "By methylation profiling, all tumors were classified as rhabdoid tumors with a corresponding subclassification within the MYC, TYR, or SHH AT/RT subgroups." (PMID 35912263, 2022).
sarcoma (4 papers, 2017 to 2021). A usually aggressive malignant neoplasm of the soft tissue or bone. "Importantly, inhibition of the SHH pathway significantly inhibits the growth of sarcoma cells with high NKX6-1 expression, indicating possible new treatment options for LMS patients." (PMID 33906647, 2021). "Although we did not see effects of SHH exposure on cell viability or proliferation, we did see increased apoptosis in RMS and EWS cells and reduced viability and proliferation in EWS cells with GANT61 treatment, suggesting fundamental roles for GLI1 in the biology of these sarcoma cell lines." (PMID 32493277, 2020).
Septo-optic dysplasia (4 papers, 2020 to 2024). Septooptic dysplasia (SOD) is a clinically heterogeneous disorder characterized by the classical triad of optic nerve hypoplasia, pituitary hormone abnormalities and midline brain defects. "Furthermore, mutations in SHH are also associated with septo‐optic dysplasia (SOD), characterised by eye defects, midline brain abnormalities, pituitary gland anomalies and optic nerve hypoplasia." (PMID 37794731, 2024). "The identification of causative variants in SHH and ARID1A further expands the phenotypic spectra associated with these genes and reveals novel pathways to explore in septo-optic dysplasia." (PMID 35885948, 2022). "The identification of causative variants in SHH and ARID1A further expands the phenotypic spectra associated with these genes and identifies novel pathways to explore in septo-optic dysplasia." (PMID 35885948, 2022).
Anophthalmia (3 papers, 2009 to 2024). Absence of the globe or eyeball. "Indirectly, SHH may also mediate the local effects of OTX2 mutations on both eye and jaw in human micro/anophthalmia with or without otocephaly and micro/agnathia." (PMID 30073412, 2019).
Cerebellar hypoplasia (3 papers, 2019 to 2024). Cerebellar hypoplasia is a descriptive term implying a cerebellum with a reduced volume, but a normal shape and is stable over time. "Seminal work in the Ts65Dn mouse model implicates reduced responsiveness to Sonic Hedgehog (SHH) as a potential cause for this cerebellar hypoplasia." (PMID 31839007, 2019). "It is interesting to note that SHH signaling has also been implicated in the development of cerebellar hypoplasia in DS." (PMID 31839007, 2019). "Our study also does not rule out the possibility that Fga−/− mice are protected from cerebellar hypoplasia through pleiotropic mechanisms involving multiple pathways beyond the promotion of SHH signaling in CGNPs." (PMID 39042684, 2024). "We previously showed that a reduced mitogenic response to SHH underlies cerebellar hypoplasia in Ts65Dn mice but lacked a clear understanding of which trisomic genes contribute to this phenotype." (PMID 36995257, 2023).
cervical carcinoma (3 papers, 2021 to 2025). A carcinoma arising from either the exocervical squamous epithelium or the endocervical glandular epithelium. "In the study of cervical cancer, it was found that empagliflozin could activate AMPK phosphorylation, down-regulate the expression of FOXA1, and thus inhibit the expression of SHH, inhibit the malignant proliferation of cervical cancer cells and induce apoptosis." (PMID 40007997, 2025).
cleft palate (3 papers, 2016 to 2020). Cleft palate is a fissure type embryopathy that affects the soft and hard palate to varying degrees. "As mutations affecting each of multiple components of both the FGF and SHH signaling pathways have been associated with CL/P in humans, our results provide significant new insight into the mechanisms regulating palatogenesis and cleft palate pathogenesis." (PMID 26745863, 2016). "SHH signalling is also implicated in palatal development, with Cyp26a1 and Cyp26b1 expression decreased and a concomitant increase in RA signals in Shh LOF mutants displaying cleft palate phenotypes." (PMID 32151018, 2020). "Notably, SHH has been implicated in the regulation of palatal fusion by TGF-β3, and abnormal SHH signaling in mice is associated with cleft palate." (PMID 32581832, 2020).
congenital malformations (3 papers, 2012 to 2021). "Anyway, Fstl1 mutant mice provide a good model to study the mechanisms of the interaction between SHH and BMP signaling pathways to regulate cell proliferation and differentiation during ureter development and in congenital malformations of the urinary tract." (PMID 22485132, 2012).
endometrial cancer (3 papers, 2021 to 2025). Primary or metastatic malignant neoplasm involving the endometrium (mucous membrane that lines the endometrial cavity). "Our study explores the relatively unexplored territory of the Sonic Hedgehog (SHH) pathway in the context of Endometrial Cancer." (PMID 39408773, 2024). "Similarly, enhanced SHH signaling may be associated with the progression of endometrial cancer." (PMID 34063525, 2021). "Notably, ZBTB3 regulates the transcription of sonic hedgehog (SHH), with SPOP inactivation leading to ZBTB3-dependent SHH upregulation in endometrial cancer cells." (PMID 40521202, 2025). "Moreover, the aberrant expression of key components of the SHH signaling pathway may serve as a prognostic factor for recurrence and survival in patients with endometrial cancer." (PMID 34063525, 2021).
fatty liver (3 papers, 2016 to 2024). "In particular, HF + ShH normalized HF-induced hepatic steatosis." (PMID 33567531, 2021).
gastric tumors (3 papers, 2019 to 2023). "In addition, apatinib treatment increased apoptosis-related proteins expression, decreased cell proliferation-related proteins expression, and inhibited SHH pathway proteins expression in gastric tumors." (PMID 34350176, 2021).
hydronephrosis (3 papers, 2012 to 2023). Collection of urine in the renal pelvis that results in dilatation of the renal pelvis and calyces. "Later, mice with a complete loss of Shh were reported to display with 50% penetrance bilateral renal aplasia or hydroureter and hydronephrosis indicating a more profound role for SHH in the development of the complete upper urinary tract." (PMID 28797033, 2017).
inflammatory bowel disease (3 papers, 2016 to 2025). A spectrum of small and large bowel inflammatory diseases of unknown etiology. "The anti-inflammatory effects of SHH are also supported by reduced HH signaling activity in the colonic mucosa of inflammatory bowel disease (IBD) patients." (PMID 40003307, 2025).
lung squamous cell carcinoma (3 papers, 2013 to 2022). "For instance, overexpression of PEBP4 results in the PI3K/Akt and SHH pathways activation, whereas PEBP4 silencing activates the ERK and MAPKs pathways in lung squamous cell carcinoma." (PMID 36120358, 2022).
malignant glioma (3 papers, 2017 to 2024). A grade III or grade IV glioma arising from the central nervous system. "Aberrant activation of sonic hedgehog (SHH)/glioma-associated oncogene homolog 1 (GLI1) pathway plays an important role in the tumorigenicity of malignant glioma cells and resistance to temozolomide (TMZ)." (PMID 28446712, 2017). "In preclinical studies with orthotopic malignant glioma xenografts, pharmacological SHH pathway inhibition significantly improved survival rates by targeting CD133 + tumour-initiating cells responsible for tumour initiation and maintenance." (PMID 39568072, 2024). "So, we assessed whether aspirin could be an effective agent in the treatment of malignant glioma via inhibiting the SHH/GLI1 signaling pathway pharmacologically." (PMID 28446712, 2017).
myelofibrosis (3 papers, 2021 to 2023). A partial or complete replacement of the bone marrow stroma by fibrous tissue. "We recently demonstrated that IGFBP-6/SHH/TLR4 axis is implicated in alterations of the primary myelofibrosis microenvironment and that IGFBP-6 may play a central role in activating SHH pathway during the fibrotic process." (PMID 36836615, 2023). "In conclusion, our results suggest that the IGFBP-6/SHH/TLR4 axis is implicated in alterations of the primary myelofibrosis microenvironment and that IGFBP-6 may play a central role in activating SHH pathway during the fibrotic process." (PMID 34905501, 2021).